CD69 (CD69 molecule)
Diseases named in the same sentence as CD69 in open-access papers (continued):
Sharing a sentence is not in itself a finding about the gene and the disease.
infection (continued). "The numbers of cluster B4 were decreased in infected PB, and analysis of their differentially expressed genes revealed that cluster B4 was enriched in Cd69 after infection." (PMID 37039643, 2023). "A representative infection of CD69+/CD103+ TRM cells is provided, along with results from 10 donors." (PMID 36897929, 2023). "In concordance with the data obtained with 2D co-cultures, upon HDV-infection, spheroid co-cultured NK cells demonstrated an increase in CD69 expression." (PMID 38143742, 2023). "Splenic IAV-specific CD4 T cells were also activated by the re-infection, increasing their expression of CD69 and ICOS, although the expression of Ifnγ was equivalent to that in memory animals." (PMID 37842651, 2023). "Within lymphoid cells, we noted higher expression of the activation marker CD69 on CD4+ T cells at day 7 in severe/critical disease compared to either pre-infection or mild/moderate disease." (PMID 36522333, 2022). "This indicated that there was enhanced CD4+ T cell priming at week 2 post infection in Mtb-HT1 infection as the appearance of CD4+CD69+ T cells is the first evidence of CD4+ T cell priming in the lymph nodes during Mtb infection." (PMID 35173157, 2022). "The results showed that PRRSV infection induced the dominant activation of CD4 T cells in mediastinal lymph nodes and CD8 T cells in the spleen at 14 days post-infection, in terms of CD69 expression." (PMID 35746813, 2022). "While the infection of total PBMCs led to the activation of the different cell subsets, as evidenced before, the proportion of CD69-expressing CD4+ and CD8+ T cells, B cells, or NK cells among lymphocytes was not increased when monocytes were depleted." (PMID 35615366, 2022). "The primary infection mainly resulted in CD11a+ TRM subsets with variable expression of CD69+ and/or CD103+." (PMID 36003372, 2022). "In contrast, during influenza virus heterosubtypic infection, CD69+ CD103- TRM cells predominate over CD69+ CD103+ TRM cells and some contribution from the circulation is also observed." (PMID 35108347, 2022). "This reduction in these central memory-like cells at d14 was preceded by a reduced proportion of CD69-/CD25+ cells at d5 post-infection." (PMID 35944008, 2022). "At seven months post infection the frequencies of CD69-expressing T helper cells in spleen, ILNs and MesLNs and cytotoxic T cells in ILNs were slightly increased." (PMID 36275685, 2022). "The marked increase in B cell recruitment observed in response rhMPV-ΔG infection was paralleled by an upregulation of the activation markers CD69 on day 9 p.i. and CD86 on days 7 and 9 p.i., compared to rhMPV -WT infection." (PMID 35958551, 2022). "We used CD69 as a readout to assess the early activation of immune cells after infection with a genotype II ASFV strain HLJ/18." (PMID 35746813, 2022). "Surprisingly, not all Unconventional T cells, such as MAIT cells, recovered their ability to produce IFN-γ and the expression of CXCR3 after infection though maintained CD69 and PD1 expressed." (PMID 35159352, 2022). "In naïve mice, CD4+CD69+CD11a+ T cells were scarce but from 3 dpi the frequency was significantly increased with a peak in numbers by day 8 post infection." (PMID 36275685, 2022). "NK cells expressed significantly higher levels of CD69 in MLNs during T1L infection than during T3D-RV or mock infection and more modestly in PPs." (PMID 35993365, 2022). "We further investigated MAIT cells by including an activation marker (CD69) and observed a higher expression (p < 0.05) of the marker in symptomatic patients throughout the infection compared to asymptomatic patients until 1 month (Day 28)." (PMID 36248882, 2022). "Surprisingly, this subset persisted when total cell numbers normalised 10 weeks post-infection and 4 weeks after deworming, leaving fewer CD69+ CD103+ cells in the skin of long-term infected and dewormed mice." (PMID 34931000, 2022).
infection (continued). "P&S induced significantly higher levels of lung-resident antigen-specific CD4+ T cells that phenotypically resemble infection-induced CD4+ T cells (IV-CD45−tetramer+CD69+CD4+)." (PMID 36302057, 2022). "The activation state of immune cells after infection or immunization was routinely determined by detecting CD69 expression, along with other markers in human and mouse models." (PMID 35746813, 2022). "Although mAbs against porcine CD69 were reported, it remains to be validated for the detection of the early activation of immune cells in pigs, following infection and immunization." (PMID 35746813, 2022). "Indeed, the computed top DEG, typifying each cluster on day 3 in the effector phase of infection, hosted several interferon-induced anti-viral genes (Irf1, Irf7, Ifrd1, Socs1, Socs3, Ifit1, Bst2, and Isg15) as well as genes associated with mature resident Trm cells (Cd69, Nfkbid, Brd2, FosB)." (PMID 35260804, 2022). "Since infection of PBMCs with ORFV led to an increase of CD69+ cells among lymphocytes, we sought to investigate the role of monocytes in the activation of other cell subsets." (PMID 35615366, 2022). "A more detailed analysis of CD69 and CD103 expression revealed that at day 1 post re-infection there was an increase in CD69+ CD103- CD8+ T cells and between days 3–4 both CD69+ CD103- and CD69+ CD103+ CD8+ T cells expanded in the lung." (PMID 35108347, 2022). "Expression of tissue resident T cell markers CD103, CD69 and CD11a remained stable at high levels in the lung tissue resident Treg cells during secondary infection, as compared to the lung circulating Treg, dLN-Treg and spleen-Treg cell subsets (column 3-5)." (PMID 36159872, 2022). "TNF-α was only significantly increased at 6 d.p.i; IL-6 was significantly increased at 3 and 6 d.p.i; IFN-γ and NOX2 were significantly increased at 3 and 6 d.p.i, and CD69 showed persistent elevation over the 6 days of infection." (PMID 35930608, 2022). "Compared to pre-infection levels, the percentage of lymphocytes expressing the early activation marker CD69 increased immediately after primary infection on NK cells and CD8 T cells, while it peaked at about 2 weeks post-infection for CD4 T cells." (PMID 35493734, 2022). "High expression of CD69 by NK cells was sustained 6.5 days after infection with MCMV-Δm15, suggesting that these cells continue to encounter antigen." (PMID 34358016, 2021). "In participants who initiated treatment in the chronic phase, CD69 expression on monocytes was decreased at 12-months post-infection compared to early treated individuals (p=0.014) but with recovery at 12-months post-ART initiation." (PMID 34630420, 2021). "While a relatively low fraction of CD4 T cells were characterized as TRM early after infection, a large percentage expressed TRM cell markers (CD69+CD11a+) during the encephalitic stage of infection." (PMID 34587172, 2021). "Strikingly, the frequency of CD69 expression on TIGIT+NK cells at different stages of infection was significantly higher than the TIGIT−NK counterparts (all P < 0.0001) and both subsets were higher than their respective HIV-1-negative donors." (PMID 33717085, 2021). "High amounts of CD44+ and CD69+ T-lymphocytes are present in both lymphatic organs in the early phase of infection." (PMID 34202636, 2021). "FACS analysis of splenic T cells concerning the presence of CD69 showed that mice treated with anti-IL-2 mAb had increased numbers of CD4+CD69+ splenic T cells 21 days after initial infection." (PMID 34869064, 2021). "We detected CD69 expression on similar proportions of cells transferred into B6 and pMT-10 mice, up to day 16 after infection, when there was a reduced expression of CD69 evident in P25Tg cells transferred into pMT-10 mice." (PMID 34554927, 2021). "During ex vivo infection, the release of monocytic cytokines and the up-regulation of early activation antigen CD69 on monocytes were markedly lower in post-operative blood." (PMID 34103589, 2021).
infection (continued). "Residual MAIT cells in chronic HCV-infection showed an activated phenotype with high levels of granzyme B, HLA-DR, PD-1 and CD69 expression and granzyme B levels remain high after successful cure." (PMID 34951583, 2021). "Upon infection, frequencies of CD69+CD103+ Tγδ17 cells with respect to total Tγδ17 cells significantly increased in the parenchyma of lung and BLF with the highest frequencies in the latter." (PMID 33772013, 2021). "Consistent with human data, both strains of IAV induced early MAIT cell activation with marked increase of granzyme B expression by day 3 and upregulation of the activation markers CD25 and CD69 peaking at day 5 post infection." (PMID 35381137, 2021). "Both IN infections generated CD69+ CD103 and CD69+ CD103+ P14 s within the mLN at 30 days post-infection; however, the frequency of CD69+ CD103+ P14 cells was lower in Vac-GP33 infected mice." (PMID 34143731, 2021). "The reduced migration of CD4+ T cells to the lung parenchyma of pMT-10 mice was associated with reduced frequencies of CD4+ T cells expressing the early activation marker CD69 at day 23 after infection." (PMID 34554927, 2021). "Stimulation of PBMCs by MEDI5395 infection led to the activation of specific leukocyte effector populations, as measured by the increased expression of CD69 on both T cells and NK cells." (PMID 32088771, 2020). "In these four participants, the cause of transplant failure reported by their nephrologists was recurrent UTIs, suggesting that this infection contributes to the development or persistence of the CD69+CD103+ MAIT cell population in the kidney." (PMID 32652598, 2020). "The potential of CD69 as an indicator to predict infection reactivation, to decrease immune protection, and to differentiate between CCs with LTBI and ATB remains to be further defined." (PMID 32849474, 2020). "Following infection and re-challenge with L. monocytogenes, a food-borne Gram-positive bacterium, intestinal CD69+CD103+ CD8+ TRM cells, respond to mediate local and protective immunity, and rely on α4β7 integrin to home to the intestine." (PMID 32858901, 2020). "Activation, measured by CD38 or granzyme B upregulation, increased during each infection in vivo whilst also in vitro MAIT cells upregulated CD69 and IFN-γ in the presence of virally-infected APCs." (PMID 32536923, 2020). "We discovered that a group of clusters of MAIT cells (clusters 6, 15, 18, and 21) was underrepresented among all CD69+ cells upon infection with STM-D23580, compared with STM-LT2, ST-Ty2, and E. coli." (PMID 32788367, 2020). "CD19+ B cells from IFNα/βR-sufficient mice displayed a significant activation (~70% CD69+) upon TMEV infection compared with the CD19+ B cells (16% CD69+) from IFNα/βR-deficient mice, suggesting the involvement of IFNα/β in B cell activation." (PMID 32727036, 2020). "Early after infection, CD69 is important for the accumulation of CD8+ T cells within the airways to inhibit strong S1P1-mediated exit signals." (PMID 33815352, 2020). "A drastically increased level of CD69 (>97% of CD19+ cells) was observed as early as 6 h after TMEV infection compared with 20–26% in uninfected cells." (PMID 32727036, 2020). "Overall, our results indicate that dl922-947 infection led to NK activation, as demonstrated by upregulation of CD69 and CD107a expression, as well as IFN-γ production." (PMID 32195317, 2020). "In adults, NK cell expression of activation markers, including CD69, perforin, and Fas-L, and myeloid cell expression of activating NK cell ligands, namely Fas, were predictive of infection." (PMID 33067399, 2020). "During infection, the proportion of CD69+ cells increased in the semen of SIV+ animals for both the Tcm (Mann-Whitney test, p = 0.002) and Tem (p = 0.0001) subsets, whereas it was higher in the blood for only Tem cells (Mann-Whitney test, p = 0.0061)." (PMID 32528466, 2020).
infection (continued). "The peak level (up to 37% of CD69+ cells) of viral proteins was detectable at 12 h post-infection, suggesting that the upregulation of CD69 on B cells after TMEV infection preceded viral protein production." (PMID 32727036, 2020). "We observed an increase in frequency and number of lung-resident CD69+ CD8 T cells precluded from circulation from cKO vs. wt animals 60 days post-infection (p.i.)(second and third panels)." (PMID 31681267, 2019). "During the acute phase of the infection, increased expression of CD69, CD38, Ki67, and granzyme B was observed on NK cells indicating activation." (PMID 31156653, 2019). "Following transduction, cells were allowed to return to a resting state as monitored by low CD69 expression before infection with HIV-1 in the absence or presence of the ligand Her2." (PMID 31116788, 2019). "CD69 is rapidly up-regulated at early stages of lymphocytes activation, for example following an acute infection." (PMID 31462286, 2019). "Sixty days following infection, we noticed a selective upregulation of CD69 in the parenchymal CD8 T cell compartment of wt and cKO mice compared to CD8 T cells circulating through the lung or spleen." (PMID 31681267, 2019). "From a total of four individual tissues, a median of 3.23% CD69+ were p24+ 3 days after infection, while only in one out of four tissues we detected few p24 positive cells (0.21%) in the CD69− fraction." (PMID 31628331, 2019). "Overall, these results indicate that infection results in populations of CD49a+, CD69+, CD8+ memory T cells that reside in peripheral tissues: tissue resident memory T cells." (PMID 31635290, 2019). "In contrast, TRM populations generated in laboratory mice following a single infection are generally smaller than circulating T cell populations and nearly all CD69+/CD103+." (PMID 31801067, 2019). "In order to demonstrate that CD4+ TRM from cervix represent a significant cellular reservoir, we first aimed to address if this subset supports infection ex vivo and which are the dynamics of CD69 after HIV infection in these tissues." (PMID 31628331, 2019). "A similar pattern of activation marker expression was seen for CD69 as well as for CD38, the latter depicted as median fluorescence intensity (MFI), albeit with lower percentages of CD69 expression on CD56bright NK cells during the acute phase of infection." (PMID 31467285, 2019). "The expression of CD69 [mean fluorescence intensity (MFI) value] on the surface of Tfh cells from the infection group was significantly higher than that of the control group (P < 0.05)." (PMID 31572373, 2019). "After malaria infection, NK cell activation as defined by upregulated CD69 expression was determined daily from day 6 post-infection until 3 days after antimalarial treatment." (PMID 31921133, 2019). "Activation of T cells, as evidenced by CD69 up-regulation was detected in lungs and mediastinal lymph nodes on day 2 post lethal infection and on day 6 following sub-lethal infection." (PMID 31443439, 2019). "CD69 is a membrane protein which is activated early in infection, usually within 2 hours of T cells stimulation in vitro with mitogens." (PMID 31600250, 2019). "While no induction of IFN-γ expression was detectable in splenic NK cells, respiratory IAV infection induced a significant increase in CD69 expression on splenic NK cells in WT mice by day 4 post infection." (PMID 29497422, 2018). "The possibility that differences in CD69 induction are indeed determined by the infection rate of monocytes is further supported by three observations." (PMID 29472914, 2018). "Using murine experimental challenge with two strains of influenza A virus, we show that MAIT cells accumulate and are activated early in infection, with upregulation of CD25, CD69 and Granzyme B, peaking at 5 days post-infection." (PMID 30413689, 2018).
infection (continued). "(C) Virus-specific CD4 +T cells and CD69 expression on CD4 +T cells in peripheral blood at early time points post-infection (p.i.)(n = 7–8 mice per genotype)." (PMID 29848443, 2018). "Expression of CD25 and CD69 peaked at day 5 post-infection and was significantly higher in MAIT cells than conventional CD4+ or CD8+ T cells, persisting until day 13 post-infection." (PMID 30413689, 2018). "The preferential infection of CD32+ cells in one donor (D2) was associated with significantly higher CD4 T-cell activation as measured by HLA-DR and CD69 expression, further indicating that CD32 expression is a marker of T-cell activation." (PMID 30013105, 2018). "Lung-resident memory CD4 T cells are primarily identified by CD69 expression following infection or vaccination." (PMID 30233573, 2018). "Respiratory IAV infection potently induced CD69 expression by lung NK cells in WT mice on days 3 and 4 post infection." (PMID 29497422, 2018). "Remarkably, a high percentage of infant circulating CD4+ T cells that expressed CD69 at the time of the first challenge strongly correlated with a low number of challenges to infection (r = −0.75, P = 0.003)." (PMID 29359183, 2018). "This memory T cell subset is established late during resolution of primary infection of those tissues, has a distinct genetic signature, and is often defined by the cell surface expression of CD69, CD103, CD49a, and CD44 in both mouse and human studies." (PMID 29632527, 2018). "This was clearly delayed in TLR7ko mice, which displayed a significantly reduced frequency of activated CD69-expressing NK cells in the lung on day 3 post infection compared to WT mice." (PMID 29497422, 2018). "The proportion of variation in the number of challenges to infection explained by the percentage of CD4+ T cells that expressed CD69 was estimated to be 0.36 as determined by a discrete-time Cox model with percent CD4+ T cells specified quadratically." (PMID 29359183, 2018). "We found that KLRG1−/CD69+ tissue-resident memory T cells (Trm) in the liver of naïve mice and 7 weeks after infection with Lm express high levels of ARTC2.2 and P2X7." (PMID 30038627, 2018). "When disease, inflammation or infection is present, CD69+ activation increases on CD4+ and CD8+ cells, and is used as an early indicator of T-cell activation." (PMID 30126153, 2018). "We have recently reported that infection of mice with B. pertussis induce the development of CD69+CD103+/− CD4 TRM cells in the lungs." (PMID 30147701, 2018). "We noted that a higher proportion of NP366−374-specific CD8+ T cells in the Clec9A-DTR group expressed the activation marker, CD69, compared with those found in the wild type group on day 10 of infection." (PMID 30622538, 2018). "Generally, NK cell activation, i.e., the significant induction of CD69 expression and also the shift toward a higher frequency of CD27highCD11blow NK cells, was stronger at the site of infection than in the periphery." (PMID 29497422, 2018). "In contrast, SIVagm GU1N infection induced a 3- to 5-fold increase in circulating CD8+ CD69+ T cells, while WT SIVagm had only minor effects." (PMID 29636452, 2018). "When the presence of activated CD8+ T cells was evaluated, an increased number of activated CD8+CD69+ T cells were detected in the lungs of WT mice at weeks 2, 4, and 10 of infection." (PMID 28740491, 2017). "Spleen CD4+ T-cell activation as measured by CD69 expression was also significantly diminished 12-days post infection." (PMID 28262829, 2017). "In contrast to brain infection with LCMV, which showed that CD103 was expressed only on a portion of bTRM, we observed that the vast majority of CD8+ T cells co-expressed CD103 and CD69 in WT mice during long-term infection." (PMID 28407741, 2017). "Co-expression of CD69 and CD103 is considered a hallmark of tissue-resident memory cells that have alarming function and serve as first responders to pathogens on site of infection." (PMID 28337201, 2017).